HIF1A (hypoxia inducible factor 1 subunit alpha)
Diseases named in the same sentence as HIF1A in open-access papers (continued):
Sharing a sentence is not in itself a finding about the gene and the disease.
tumor (continued). "The results showed that the proportion of HIF-1α-positive cells was low in the tumor tissue that was just isolated, and the proportion of HIF-1α-positive cells did not change even after the tissues were cultured." (PMID 33659211, 2020). "In conclusion, our research uncovered IL-37/STAT3/HIF-1α negative feedback signaling drives tumor development and Gem resistance in PDAC." (PMID 32226541, 2020). "There was a statistically significant difference in the immunoexpression of HIF-1α, MMP-2, VEGF/VEGFA, and VEGFR-2 proteins between the parenchyma of tumour cells and the stroma of tumour cells, where the parenchyma cells of AME showed a higher immunoexpression compared to the stromal cells." (PMID 33067558, 2020). "Geniposide inhibited secretion of VEGF by HCC and suppressed the migration of endothelial cells and the formation of intra‐tumour blood vessels, without cytotoxicity and independently of the transcription factor HIF‐1α." (PMID 32144747, 2020). "A hypoxic tumor microenvironment triggers the activation of various genes that regulate cell survival, proliferation, and growth, and consequently escalates the generation of ROS in tumors by HIF-1α (hypoxia-inducible factor 1 alpha) and its target genes." (PMID 32354000, 2020). "While correlative studies of human ccRCC and functional studies using human ccRCC cell lines have implicated HIF-1α as an inhibitor and HIF-2α as a promoter of aggressive tumour behaviours, their roles in tumour onset have not been functionally addressed." (PMID 32807776, 2020). "In a further exploration of the molecular mechanisms underlying the hypoxia‐induced aggressive tumor phenotype of BC, we found that, as a potential tumor suppressor, miR‐141–3p counteracted hypoxia‐induced migration and suppressed the hypoxia‐activated HMGB1/HIF‐1α pathway." (PMID 32436353, 2020). "Hypoxia drives expression of the well-defined transcription factor HIF1α, which promotes the expression of ectoenzymes CD39 and CD73 on tumor cells, stromal cells, and tumor-infiltrating immunosuppressive cell subsets, such as regulatory T cells (Tregs) and myeloid-derived suppressor cells (MDSCs)." (PMID 32244422, 2020). "In turn, HIF-1α is conducive to the adjustment of tumors to hypoxia through transcriptional activation of more than 100 downstream genes including LEP, EPO, PKM, etc.; in this regard, HIF-1α further promotes the proliferation of tumor cells." (PMID 33681184, 2020). "Immunohistochemistry staining of HIF-1α further affirmed the effects of Nb@IC-NPs on the mitigation of tumor hypoxia, whereas the same result was not noticed in IC-NPs group that was lack of a specific targeting." (PMID 33292202, 2020). "Besides, the increased expression of GLUT-1, HIF-1α, p-AKT and p-AMPK were also detected in Vitamin K2-treated tumor group." (PMID 32382009, 2020). "Interestingly, the OA-treated tumor spheroids exhibited greater expression of FABP5 and HIF-1α and grew faster compared with vehicle-treated spheroids; this was abrogated by FABP5 or HIF-1α knockdown." (PMID 33128030, 2020). "In addition, tumor signaling pathways that are regulated by BRAF, HIF-1α, c-MYC, and mTOR are accelerated to activate glycolysis in the cancer cells and accumulation of lactate in the microenvironment of the tumor." (PMID 32213878, 2020). "Furthermore, curcumin and Glu-GNPs downregulated the HIF-1α and HSP90 expression in both types of tumor spheres." (PMID 33457406, 2020). "Therefore, further studies of direct regulation between HIF‐1a and miRNAs or SIRT5 need to be broadened, and we will expound more upon the function of miR‐3677‐3p in different tumour microenvironments." (PMID 32596968, 2020). "Finally, the levels of acetyl-CoA and NAD+ in hypoxic tumors were reduced, which seemed to contradict their ability to stabilize HIF-1α and HIF-2α and promote tumor progression." (PMID 33109235, 2020).
tumor (continued). "Moreover, immunohistochemical staining showed a marked decrease in HIF-1α, VEGFA, and CD31 expression in 20(S)-Rg3 group tumor tissues." (PMID 32382013, 2020). "HIF1-α, NF-κB and GM-CSF expression levels in tumour were higher, and CD33 + MDSCs showed an increased retention in the tumour stroma, whereas CD8 + lymphocyte numbers in tumour epithelium were markedly reduced after bevacizumab treatment." (PMID 31932754, 2020). "Previously demonstrated data in accordance with our results might suggest that AEZS-108 induces a well regulated signaling pathway against ECM degradation, angiogenesis and migration of tumor cells via the regulation of MASPIN, HIF1A and their target genes." (PMID 32010430, 2020). "Upregulation of HIF-1α in normoxia is a feature of tumor cells and different non-canonical modalities of HIF-1α modulation have been identified." (PMID 32413989, 2020). "Since FAT1 and NFкB (RelA) are independently known to promote pro-tumorigenic inflammation and upregulate the expression of HIF-1α/EMT/stemness in tumors, targeting the NFкB (RelA)-FAT1 axis may attenuate an important tumor-promoting pathway in GBM." (PMID 31992226, 2020). "Elevated HIF-1α protein expression promoted the secretion of vascular endothelial growth factor (VEGF), which mediated tumor-protective response to radiotherapy via vascular protection or inhibiting IR-induced apoptosis by upregulating anti-apoptosis protein, Bcl-2." (PMID 32403326, 2020). "Hypoxia-inducible factor 1-alpha (HIF-1α) and vascular endothelial growth factor (VEGF) are two critical elements in tumor angiogenesis, and both are up-regulated upon MYC activation both in tumor cells and TAMs." (PMID 33081056, 2020). "In addition, endostatin can reduce the expression levels of VEGF, TGF-β, IL-6, and IL-17 in tumor tissues, increase the expression levels of IFN-γ and HIF-1α, suppressing growth and angiogenesis of tumors." (PMID 33224886, 2020). "HIF-1α accumulation contributes to glycolysis by enhancing transcription of glycolysis-related genes, including GLUT1, HK2, ALDOA, PKM2, and LDHA, which was the most important method for tumor cells to get energy and growth." (PMID 33244454, 2020). "Using a paired T-test, we found that the HIF-1α score was significantly higher in lymphatic metastasis tissues than in primary lesions, which is consistent with the conclusion of previous studies that HIF-1α is closely related to tumour metastasis." (PMID 32093760, 2020). "Moreover, deletion of c-Myc in macrophages resulted in the reduced expression of pro-tumor genes (e.g., VEGF, MMP9, and HIF1a) in TAMs and reduced tumor development in a mouse model of melanoma." (PMID 32486098, 2020). "In triple-negative breast cancers, upon hypoxia, XBP1 cooperates with HIF1a to promote tumour growth and foster relapse by activating pathways such as angiogenesis and glucose metabolism." (PMID 32111004, 2020). "The discrepancies between studies indicate that the roles of HIF-1α and HIF-2α in mediating PD-L1 expression may depend on the cell type and type/location of the tumor." (PMID 32316260, 2020). "In addition, YAP1 can increase and sustain HIF1A protein stability, thereby establishing a HIF1A/YAP1 positive feedback loop that mediates Nic-stimulated EMT and tumor progression in PDAC." (PMID 32894161, 2020). "Moreover, IFN-γ increases HIF-1α expression in MSCs, which in turn, upregulates VEGF expression and promotes tumor angiogenesis." (PMID 32993787, 2020).
tumor (continued). "In human PCa C38 and C27 cells, zinc could induce proteasomal degradation of HIF-1α and consequently reduce HIF-1α recruitment to the VEGF promoter and its transactivation of this target gene, leading to decreased invasiveness and tumor formation." (PMID 31963946, 2020). "It remains to be seen, for example by overexpression of non-degradable HIF-1α, to what extent inhibition of hypoxic responses by mitochondrial inhibitors contributes to overall anti-tumor activity of these agents." (PMID 32695673, 2020). "This subsequently leads to increased levels of hypoxia-inducible factor 1-alpha (HIF1α), which drives VEGF expression and could finally lead to tumor angiogenesis." (PMID 32984308, 2020). "Tumor volume, lung metastasis, and tumorigenic molecules (VEGF-A, HIF-1α, MMP-9, ICAM-1, VCAM-1, and phospho-NF-κB and phospho-STAT-3) were significantly induced in mice injected with ESM-1-overexpressing 4T1 cells and greatly enhanced in those injected with ESM-1-overexpressing RT-R-4T1 cells." (PMID 32466580, 2020). "HIF-1α is involved in SGC-7901 cell growth, apoptosis, and tumor angiogenesis." (PMID 33376737, 2020). "One of the primary responses of the hypoxic tumor is the production and activation of the oxygen/hypoxia sensing hypoxia-inducible factor-1 alpha (HIF-1α) component of the HIF-1 heterodimer (made up of HIF-1α and HIF-1β)." (PMID 32883003, 2020). "Non-selective beta-blocker propranolol decreased ability of tumour cells to adapt to hypoxia by reducing levels of HIF1α and carbonic anhydrase IX in 3D spheroids." (PMID 33228233, 2020). "Other inflammatory mediators that upregulate PD-L1 expression in tumor and non-tumor cells include IL-6, prostaglandin E2 and HIF-1α." (PMID 32992658, 2020). "We argue that HIF-1α and HIF-2α are likely to play different roles at different stages of tumour formation and progression and that these roles might potentially be modulated by the spectrum of mutations present in each individual ccRCC." (PMID 32807776, 2020). "Taken together, the data indicate that HIF1α is not a target of 14q deletion in ccRCC and that it is not a tumor-suppressor in this malignancy." (PMID 33077781, 2020). "Moreover, we explored the complex interplay between different species of RNAs, in which miR-370-3p exerts a tumor-suppressor function in GSCs by targeting HMGA2 and HIF1A mRNAs, genes involved in EMT and hypoxia." (PMID 32443824, 2020). "CD8+ lymphocytes are no exception, since their tumor suppressor activity is dampened by macrophages within TME with a HIF-1α (hypoxia-inducible factor-1α)-dependent mechanism." (PMID 33143050, 2020). "In our study we show that by leveraging the mTor dependency of HIF1-α, Temsirolimus suppresses the overshooting hypoxia response, reduces VEGF levels under normoxic and hypoxic conditions and inhibits tumor growth both in vitro and in vivo in KLF4-overexpressing tumor cells." (PMID 32245394, 2020). "Interestingly, AHR had been shown to cooperate with HIF1α through the commonly shared partner, AHR nuclear translocator (ARNT/HIF1β), to orchestrate glycolysis and tumor microenvironment." (PMID 32226544, 2020). "HIF1A and HK2 were important glycolysis regulated genes, VEGFA was tumor angiogenesis gene." (PMID 33197880, 2020). "Hypoxia‐inducible factor‐1α (HIF1A), the required subunit of HIF1, which is the main transcriptional factor in hypoxia and plays an essential role in tumour angiogenesis and proliferation, was also in the green module, and significantly up‐regulated in the MES subtype." (PMID 32091665, 2020). "Similar to breast cancer, KL might be tumor-suppressing by inhibiting IGF-1R–dependent PI3K/AKT signaling or aerobic glycolysis via ERK/hypoxia-inducible factor 1α (HIF-1α) in CRC." (PMID 33520985, 2020).
tumor (continued). "At reduced atmospheric oxygen concentration, uptake of [64Cu][Cu(ATSM)] in MCF-7 tumor cells was shown to be significantly increased, and for the first time, a strong correlation between the expression of HIF-1α and [64Cu][Cu(ATSM)] uptake by tumor cells was demonstrated." (PMID 32274601, 2020). "Furthermore, it was found that inhibition of HIF-1α expression and inhibition of CXCL12/CXCR4 signals all alleviate tumor cell migration and invasion." (PMID 32848510, 2020). "Moreover, nicotine can induce nuclear accumulation of HIF1A protein, which contributes, at least in part, to nicotine-promoted NSCLC cell migration, invasion, and tumor angiogenesis." (PMID 32894161, 2020). "ACF, as the HIF-1 inhibitor, could prevent HIF-1α/HIF-1β dimerization by binding to the dimerization domain of HIF-1α, hence inhibiting tumor cell survival pathways." (PMID 32211603, 2020). "In addition, we report that LDM administration per se is able to decrease HIF‐1α or HIF‐2α levels, wherein paralog specificity is dependent on the interaction of factors such as tumor size, cell‐autonomous, and microenvironmental effects." (PMID 32686360, 2020). "The deleterious effects of estrogen in hypoxia on ATM repression and HIF1A/VEGFA activation indicate that estrogen may also have pro-tumorigenic and pro-angiogenic effects deep within an hypoxic tumor." (PMID 33363037, 2020). "The protein levels of the HIF-1a were significantly higher in tumor tissues compared with normal tissues based on the HPA database." (PMID 32850440, 2020). "Since hypoxia-inducible factor (HIF)-1a is one of the key regulators for the differentiation and accumulation of MDSCs in hypoxic tumor regions, targeting HIF-1a might improve anti-tumor immune responses in patients with anti-PD1 Abs." (PMID 32707850, 2020). "Activation of the ERK pathway potentiates the activation of HIF-1α, NF-κB, and STAT-3, and these transcription factors are well known to be involved in the tumor growth and progression through the transcriptional regulation of various inflammatory genes, such as adhesion molecules, MMPs, and VEGF." (PMID 32466580, 2020). "The number and the size of blood vessels in Mock tumors correlated with increased tumor hypoxia indicating an active role of tumor cell-derived HIF-1α signaling leading to aberrant, non-functional angiogenesis." (PMID 33142239, 2020). "Tumor xenografts with stable expression of HIF1a were established in castrated and non-castrated mouse models." (PMID 32450824, 2020). "On the contrary, lncRNA hypoxia-inducible factor-1 alpha subunit antisense RNA 2 (HIF-1A-AS2) forms a complex with HIF-1α-mRNA, leading to a negative feedback loop, blocking angiogenesis in non-tumor tissue." (PMID 33333852, 2020). "Here we report for the first time that combined AR and HIF1a signaling in vivo promotes tumor growth and demonstrate the capacity of HIF1a to promote tumor growth in the absence of endogenous androgen in vivo." (PMID 32450824, 2020). "Interesting observation of the current study is that HIF-1α, an important transcriptional factor related with tumor apoptosis and metastasis in hypoxic tumor environment, was not changed with CIH." (PMID 32024881, 2020). "It has not been reported that ncRNAs and HIF-1α can directly affect the immune escape of tumor cells through complex molecular networks, but this indirect evidence also suggests that this idea merits further exploration." (PMID 32561709, 2020). "The stable expression of HIF1a in vivo restored tumor growth in the absence of endogenous androgens." (PMID 32450824, 2020). "Further research showed that HIF-1α upregulates BNIP3 expression under hypoxic conditions, thereby inducing Beclin1-dependent mitophagy and mitochondrial metabolic reprogramming, resulting in reduced ROS production and promoted tumour growth." (PMID 32928258, 2020).
tumor (continued). "Hypoxia inducible factor-1 alpha (HIF-1α), an upstream regulator of a variety of signaling pathways, regulates many tumor metabolic processes, such as glycolysis, apoptosis, angiogenesis, and promotion of tumor growth." (PMID 33042832, 2020). "Activated lymphocytes and other cells of the immune compartment infiltrating the tumor may release VEGF-A and inflammatory cytokines able to increase HIF-1α and consequently VEGF-A synthesis." (PMID 32085654, 2020). "Further, the activation of RSKs and HIF-1α, in addition to Ras/MEK, may be useful as novel biomarkers in tumour biopsy samples to accurately predict the efficacy of 5-ALA-PDD and PDT in clinical settings." (PMID 33335181, 2020). "While HIF-2α protein is present in the vast majority of all sporadic ccRCC tumours, HIF-1α protein expression is not detected in about 30% of cases and this correlates with increased tumour cell proliferation." (PMID 32807776, 2020). "Considering the previously reported links between lipid metabolism and tumor progression, we hypothesized that FABP5/HIF-1α plays a crucial role in cancer development." (PMID 33128030, 2020). "Accumulating evidence demonstrates that many factors, such as hypoxia inducible factor 1 alpha (HIF-1α), are involved in survival, angiogenesis, invasion and metastasis of hypoxic tumor cell, and several inhibitors targeting hypoxic tumor cells have been developed." (PMID 31964396, 2020). "HIF-1a and hypoxia are known drivers of EMT, a process that promotes tumor metastasis." (PMID 32175278, 2020). "pVHL re-introduction into 2020 cells significantly delayed tumour growth but HIF-1α knockdown did not." (PMID 32807776, 2020). "Besides, HIF-1α is not only a transcriptional regulator of LDHA, but also coordinates components of cancer development and progression and anti-tumor immunity." (PMID 32034005, 2020). "The expression levels of HIF-1α and VEGFA in tumor cells were similar to that of CD31." (PMID 32382013, 2020). "Co-staining against HIF-1α, a hypoxia marker, and CD44, a marker previously used to define perivascular and perinecrotic tumor areas, revealed that DLK1 localized prevalently in perivascular and hypoxic niches, with previously unreported nuclear localization specifically in these areas." (PMID 32205867, 2020). "HIF-1α-induced VEGF and ANGPTL4 expression can effectively promote tumor angiogenesis in melanoma." (PMID 32993787, 2020). "In addition, GC cells after omental stimulation transform to an angiogenic phenotype through HIF1α and VEGFA overexpression, which also induces tumour growth and invasion." (PMID 32439934, 2020). "The exact way this phenomenon happens is still not entirely known, but HIF-1α-depleted models show decreased tumor growth." (PMID 33143050, 2020). "HIF‐1α, GLUT1, and HK2 were stained and demonstrated in tumor cells." (PMID 32533646, 2020). "c-Myc inhibition by treatment with 10058-F4 or transduction of c-Myc by c-Myc/shRNA in human macrophages stimulated by tumor-conditioned medium from PANC-1 (human pancreatic cancer cell line) suppresses expression of protumoral genes (ALOX15, CD206, TGF-β, VEGF, HIF-1α and MMP9)." (PMID 32486098, 2020). "In this present study, we developed an alternative approach to lineage trace the fate of hypoxic tumour cells that directly reports HIF-1α stabilisation rather than the hypoxia transcriptional response." (PMID 32571767, 2020). "HIF-1a induces the expression of CD24 at the transcriptional level to promote tumor immune escape, and the non-coding RNA, Wnt/ β-catenin, promotes or inhibits the expression of CD24 to promote or inhibit tumor immune escape." (PMID 32765491, 2020).